TRIB3 (tribbles pseudokinase 3)
Diseases named in the same sentence as TRIB3 in open-access papers (continued):
Sharing a sentence is not in itself a finding about the gene and the disease.
cancer (continued). "The higher transcript levels of the key genes in the Atf4 pathway, such as Trib3 and Asns, which were observed in the ETOH-BKO livers led us to measure 4-EBP1 (EIF4EBP1), as it is a critical ATF4 gene target that is implicated in protein synthesis, metabolic and stress adaptations, and cancer." (PMID 37569418, 2023). "Approaches to inhibiting TRIB3 activity may be developed for cancer therapy." (PMID 35610288, 2022). "Through these interactions, TRIB3 has been reported to participate in processes such as the regulation of cellular stress response and cell death, megakaryocytopoiesis, metabolic adaptation to nutrient-limiting conditions, and to mediate cancer cell sensitivity to chemotherapeutics." (PMID 32745133, 2020). "We recently reported that TRIB3 promoted the initiation and progression of several cancers by interacting with the autophagic receptor p62, impairing the degradation functions of autophagy and proteasome, two critical protein quality control systems in cancer cells." (PMID 32694521, 2020). "Thus, TRIB3 plays a crucial function at the juncture of homeostasis, metabolic disease, and cancer." (PMID 31191318, 2019). "However, TRIB3 depletion partially rescued the decrease in MDA-MB-231 viability evoked by GA treatment, indicating that there could be additional (TRIB3-independent) mechanisms by which GA regulates cancer cell death." (PMID 31578236, 2019). "ELF4 can complex with TRIB3 to promote CDK6 expression, which is involved in EC cell proliferation and cancer stemness activities." (PMID 41287970, 2025). "Tribbles homolog 3 (TRIB3), an ERS and metabolic sensor, is important in chronic inflammation and cancer because it inhibits ubiquitin-mediated substrate degradation." (PMID 40292292, 2025). "On the other hand, similar to TRIB2, TRIB3 binds to EGFR and stabilizes its recycling, facilitating the development of cancer." (PMID 38731938, 2024). "In support of this idea, several cancer cells overexpress EGFR-stabilizing proteins, such as Sortilin, TRIB3, and USP22, which suppress EGFR degradation, and their knockdown inhibits cancer cell proliferation." (PMID 36410436, 2022). "We analyzed the differential expression of TRIB3 and FABP1 in different disease groups as well as in the cancer and adjacent tissues." (PMID 34957220, 2021). "The expression of ALDH1A1, a CSC marker, and the cancer stemness factors including BMI1, NANOG, and octamer-binding transcription factor (OCT4) were also reduced in both AN3CA and HEC1A cells after TRIB3 silencing." (PMID 33334065, 2020). "Taken together, high expression of both TRIB3 and EGFR is the biomarker to determine the sensitivity of cancer cells to SAH-JGZ4 treatment." (PMID 32694521, 2020). "Knockdown of TRIB3 in radioresistant MDA-MB-231 TNBC cells decreased Notch1 activation, as well as the CD24-CD44+ cancer stem cell population, and sensitized cells toward radiation treatment." (PMID 30678233, 2019). "The present study also presented evidences that the activated CHOP regulated TRIB3 expression resulting in p-AKT inhibition, indirectly display extinction effect in cell survival and cancer progression." (PMID 30176898, 2018). "We also observed the increased expression of two alternative transcripts (TRIB3: uc002wdm/NM_021158 and ICAM1: uc010xle/AK301412) in all the cancers with one exception." (PMID 28105922, 2016). "In contrast, silencing TRIB3 decreases the basal and IGF‐1‐induced accumulation of SQSTM1 in cancer cells." (PMID 27038142, 2016). "Notably, both EGFR and TRIB3 are involved in the MAPK pathway, which plays a pivotal role in cancer development." (PMID 40104395, 2025). "In common with TRIB3, a potential link between TRIB2 and HIF-1α has been reported, as depletion of TRIB2 significantly decreased the effect of TNF-α on HIF-1α stability and accumulation in multiple cancer cell lines." (PMID 38896446, 2024).
cancer (continued). "The genes—including BEST4, LMO1, ARID3C, TMEM44, FKBP10, and TRIB3—were correlated with VSX1 and might play a primary role in the transcriptional misregulation of cancer from the TCGA database." (PMID 36463181, 2022). "In conclusion, our study indicates the possibility that locally administered lidocaine for pain control in cancer patients might suppress tumor growth by increasing GDF-15 and TRIB3 expression." (PMID 36008442, 2022). "Besides, the expression of TRIB3 protein in EGC + AGC group (Cancer group, CG) was significantly lower than that in GS + IM-GA group (Non cancer group, NCG) (p < 0.001)." (PMID 34957220, 2021). "In addition, TRIB3 is necessary for EGF-induced STAT3/5 activation, which is critical for cancer stemness and chemoresistance." (PMID 32694521, 2020). "Although long-term AZD9291 treatment reduced TRIB3 and EGFR expression, it upregulated the expression and phosphorylation of STAT3, STAT5, and ERK1/2, suggesting the compensatory activation of other oncogenic pathways and induction of cancer stemness." (PMID 32694521, 2020). "These and our findings may provide a basis to develop HTS protocols to screen for anti-cancer compounds by means of qPCR-based early detection of DDIT3 and TRIB3 (t = 6 h)." (PMID 29290987, 2017). "Therefore, they conclude that the TRIB3/SQSTM1 interaction mediates the IGF‐induced the SQSTM1 accumulation, which compromises UPS as well as autophagic degradation in cancer cells." (PMID 27038142, 2016). "However, these researchers found that TRIB3 overexpression inhibits LC3‐I/‐II conversion and increases the level of both soluble and insoluble SQSTM1 in cancer cells." (PMID 27038142, 2016). "In the context of cancer cell resistance to rapamycin, a non-targeted liquid chromatography tandem mass chromatography (LC-MS/MS) proteomics combined to functional annotation clusters was conducted to complete the TRIB3 protein interaction network." (PMID 33920424, 2021). "The results show that the expression of TRIB3 in cancer tissues was significantly higher than the paracancer tissues, and confirmed by Image J (NIH, United States) which was used to densitometer quantitative analysis of TRIB3 Western blot results of 40 pairs of tissues." (PMID 33841505, 2021). "Finally, Trib3 was documented to interfere with the inflammatory MAPK signaling via direct interaction with MEK-1 and MKK7 leading to attenuation of AP-1 mediated transcriptional activity in cancer HeLa cells." (PMID 23637839, 2013).
tumor (87 papers, 2009 to 2026). "Another ceRNA putatively targeted by miR-26b-5p is TRIB3—a ferroptosis-related gene whose high expression has been associated with tumor progression." (PMID 39457549, 2024). "TRIB3 silencing was associated with significant reductions in tumor size and weight relative to control tumors." (PMID 38561354, 2024). "A recent report has similarly shown that in a CRC mouse model, T cell recruitment to the tumor was improved after TRIB3 loss, thereby sensitizing the tumor to immune checkpoint blockade therapy." (PMID 38791967, 2024). "As an independent prognostic factor, TRIB3 was associated with advanced tumor T stage and was significantly involved with tumor mutation burden and immune cell infiltration in HNSC." (PMID 38235126, 2023). "Immune landscape characterization showed that TRIB3 was significantly associated with the tumor immune microenvironment in ccRCC, including altered patterns of TILs." (PMID 35726370, 2022). "By contrast, TRIB3 was shown to have the opposite effect, and its loss was associated with a more aggressive tumor phenotype." (PMID 34198908, 2021). "One, made by Professor Guillermo Velasco, identified strong association between TRIB3 expression and apoptosis in tumour cells." (PMID 34572744, 2021). "It was revealed that high expression levels of TRIB3 were significantly associated with higher tumor TNM stage." (PMID 33841505, 2021). "Nevertheless, despite the association of upregulation with poor prognosis, TRIB3 can act as a tumor-suppressor or oncogene in a context-dependent manner." (PMID 33920424, 2021). "Nevertheless, despite the association of TRIB3 upregulation with bad prognosis, it can act as a tumor-suppressor or oncogene in a context-dependent manner." (PMID 33920424, 2021). "TRIB3 expression was also found to be associated with tumor metabolism, as revealed by the induction of mutual antagonism between autophagy and ubiquitin proteasome system (UPS)." (PMID 32874132, 2020). "M Salazar’s group has also shown that TRIB3 deletion is closely associated with a more aggressive phenotype in various tumor types by enhancing AKT activity." (PMID 30176898, 2018). "Overall, their studies prove that stress protein TRIB3 mediates metabolic risk factors‐induced tumor development and progression." (PMID 27038142, 2016). "They find that Pep2‐A2 displays a significant inhibition of SQSTM1/TRIB3 interaction in tumor cells, rescuing the TRIB3‐reduced association of SQSTM1 with LC3 and ubiquitinated proteins." (PMID 27038142, 2016). "Moreover, the inducible silencing of TRIB3 in vivo led to a substantial delay in tumor progression and was associated with prolonged overall survival, underscoring the therapeutic relevance of targeting this molecule." (PMID 40508013, 2025). "Furthermore, the correlation between TRIB3 and tumor mutation burden, clinical data, immune checkpoint genes, and immune cell infiltration was explored." (PMID 38235126, 2023). "The high protein expression of TRIB3 could inhibit the ability of tumor immune apoptosis, cause tumor cell death and prolong the survival of patients." (PMID 34957220, 2021). "Moreover, the maintenance of TRIB3 expression in the affected lymph nodes with respect to the primary tumor at the time of diagnosis is associated with a lower frequency of recurrence in these patients." (PMID 34771470, 2021). "And the high expression of TRIB3 is associated with tumor stage and poor prognosis." (PMID 32160655, 2020). "In combination these results indicate that TRIB3 might be associated with tumor cell survival under prolonged intermediate hypoxic stress." (PMID 21864376, 2011). "Next, we sought to establish whether TRIB3 is associated with poor prognosis solely as a marker for hypoxia, or that it has a functional role in hypoxia resistance of tumor cells." (PMID 21864376, 2011). "In addition, TRIB3 is closely associated with tumor immunity." (PMID 35726370, 2022).
tumor (continued). "A detailed analysis of the clinical features of each of the patients revealed that “high TRIB3” expression was associated with a more prolonged disease-free survival, an effect that was maintained when nuclear or cytoplasmic localization of the protein in the primary tumor was considered." (PMID 34771470, 2021). "By employing multiple complementary approaches, we delineated the induction, biologic function, and clinical relevance of TRIB3 in the tumor microenvironment of patients with HCC." (PMID 39932456, 2025). "Neutrophils, a key component of the tumor microenvironment, played a pivotal role in TRIB3‐elicited sorafenib resistance." (PMID 39932456, 2025). "More precisely, our results provide evidence that elevated TRIB3 promoted tumor growth, angiogenesis, and metastasis via facilitating the selective enrichment of neutrophils, as indicated by the following observations." (PMID 39932456, 2025). "TRIB3 overexpression was detected in this analysis, and this was further confirmed when specifically comparing 72 paired tumor and paracancerous samples from this dataset." (PMID 38561354, 2024). "Recently, several studies have identified TRIB3 as a crucial regulator in tumorigenesis and tumor progression." (PMID 39118481, 2024). "Moreover, miR-26b-5p could potentially inhibit TRIB3, a gene associated with tumor proliferation." (PMID 39457549, 2024). "The expression of TRIB3 in normal bladder tissues was higher than that in tumour tissues, contrary to the results for RNA expression." (PMID 38307969, 2024). "This approach revealed pronounced lipid accumulation in RCC tumor tissues in a manner positively correlated with the expression of TRIB3." (PMID 38561354, 2024). "TRIB3 overexpression was observed in both RCC patient tumor tissues and cell lines, and this upregulation was correlated with a worse RCC patient prognosis." (PMID 38561354, 2024). "In subsequent mechanistic analyses, TRIB3 was found to promote the accumulation of LDs in tumor cells through its ability to stabilize PLIN2, thereby alleviating ER stress and facilitating more rapid progression of ccRCC." (PMID 38561354, 2024). "Targeted inhibition of TRIB3 has been shown to turn “cold tumor” hot and play an important role in BC progression." (PMID 39881875, 2024). "The TRIB3/STAT1/CXCL10 axis modulated the infiltration abundance of CD 8+ T cells in tumor tissues, leading to the immune escape phenomenon." (PMID 38604154, 2024). "Tumor TRIB3 is primarily located in malignant cells, mediating their progression, and it is also widely expressed in the immune cells of the TME." (PMID 38235126, 2023). "TRIB3 was significantly upregulated in tumor tissues in TCGA-KIRC database and its expression in A498 cells was dramatically elevated compared with that in HK2 cells." (PMID 38006403, 2023). "Subsequently, we comprehensively explored the influence of TRIB3 on tumor growth and development by conducting cell viability assays, assessment of cell proliferation and migration capacity and colony formation experiments." (PMID 38006403, 2023). "The results showed that TRIB3 was not only expressed in malignant tumor cells but also broadly expressed in most types of immune cells." (PMID 38235126, 2023). "Univariate Cox regression analysis was performed to investigate the impact of age, gender, grade, tumor stage, tumor grade, and TRIB3 expression level on HNSC patient prognosis." (PMID 38235126, 2023). "To address the putative roles of Cbx6, Trib3, and Etv4 as downstream effectors of the tumor promoting effect of Kdm5c KD, we assessed the consequences of KD of either of them in combination with Kdm5c KD." (PMID 36631623, 2023). "As expected, RT-qPCR analyses revealed a significantly elevated expression of TRIB3 in the tumor tissues than in normal adjacent tissues." (PMID 38235126, 2023). "Meanwhile, the relatively elevated chromatin accessibility of TRIB3 in tumor epithelial cells was manifested in the scATAC data." (PMID 37153569, 2023).
tumor (continued). "Of particular interest is the fact that we found that TRIB3 expression was higher in tumor epithelial cells referred to normal epithelial cells." (PMID 37153569, 2023). "Here, the expression status of TRIB3 transcriptomic data across 21 tumor types was assessed, and it revealed that TRIB3 RNA levels were elevated in almost all tumors." (PMID 38235126, 2023). "Then, the expression levels of TRIB3 in overall cancerous and normal tissues, as well as between tumorous tissues and their paired normal counterparts, were compared." (PMID 38235126, 2023). "TRIB3 expression was notably higher in RCC tissues in comparison to paracancerous tissues, and elevated TRIB3 expression correlated with advanced tumor stage and an unfavorable prognosis." (PMID 38090559, 2023). "Here, we found that tumor tissues had a significantly higher TRIB3 expression level than normal tissues." (PMID 38006403, 2023). "The results showed that age, TRIB3, and tumor stage were potential factors affecting the prognosis of HNSC patients." (PMID 38235126, 2023). "Simultaneously, we explored the DEGs related to TRIB3 expression and potential signaling pathways related to TRIB3 and clarified the correlation between TRIB3 and tumor-infiltrating immune cells in ccRCC, which is novel and of great significance." (PMID 35726370, 2022). "And the expression of TRIB3 is strictly correlated with the progression of several tumor types, including breast cancer, colorectal cancer and glioma." (PMID 35473511, 2022). "In mechanism, TAMs produce the cytokine TGF-β to support the expression of HIF1α, thereby up-regulating Tribbles pseudokinase 3 (TRIB3) in tumor cells." (PMID 35836256, 2022). "Similar results were obtained for the evaluation of TRIB3 in 72 pairs of tumor samples and paracancerous tissues in TCGA dataset, which showed that TRIB3 was expressed at significantly higher levels in ccRCC tissue than in normal kidney tissue (p < 0.001)." (PMID 35726370, 2022). "Collectively, those results suggested that integrin αvβ3 induced tumor progression was TRIB3 dependent." (PMID 35473511, 2022). "In this research, we discovered a positive relationship between TRIB3 expression and tumor stage, and high levels of TRIB3 indicating a poorer survival." (PMID 35610288, 2022). "Concurrently, we explored DEGs related to TRIB3 expression and potential signaling pathways involving TRIB3 and clarified the correlation between TRIB3 and tumor-infiltrating immune cells in ccRCC." (PMID 35726370, 2022). "The following year, another article showed elevated gene expression of TRIB3 in different tumor cell lines." (PMID 34198908, 2021). "As anticipated, TRIB3-OE mice showed a heavier tumor burden, reflected by a decrease in respective survival rates." (PMID 34198908, 2021). "Clinical studies report an increased TRIB3 expression in tumor tissue as compared to normal tissue and a correlation with poor prognosis." (PMID 33920424, 2021). "Another mechanism by which TRIB3 can contribute to tumor suppression is via the interaction with the anti-viral cytidine deaminase APOBEC3A (Apolipoprotein B mRNA Editing Enzyme Catalytic subunit 3A)." (PMID 33920424, 2021). "The principal mechanism by which TRIB3 inhibits tumor progression probably relies on the inhibition of the phosphorylation/activation of Akt resulting in reduced pro-survival action." (PMID 33920424, 2021). "Tribbles pseudokinase 3 clearly has a role in tumor progression, either as tumor suppressor or as oncogene." (PMID 33920424, 2021). "In accordance, data from TCGA confirm that TRIB3 mRNA expression is higher in the tumor tissues compared to the normal tissues." (PMID 33920424, 2021). "Clinical studies report an increased TRIB3 expression in tumor tissue as compared to normal tissue, and this correlates with poor prognosis." (PMID 33920424, 2021). "We found that both TRIB3 mRNA and protein levels were upregulated in tumor samples when compared with normal breast tissue." (PMID 34771470, 2021).